CD4 (CD4 molecule)
Diseases named in the same sentence as CD4 in open-access papers (continued):
Sharing a sentence is not in itself a finding about the gene and the disease.
Splenomegaly (119 papers, 2007 to 2026). Abnormal increased size of the spleen. "Consistently, aged Tdrd3fl/fl/Foxp3YFP-Cre mice developed spontaneous autoinflammatory symptoms, including splenomegaly, weight loss, and lymphocytic infiltration in the lungs and liver, with CD4+ T cells producing elevated levels of inflammatory IFN-γ." (PMID 41576154, 2026). "Myeloid-specific Znrf1 deletion caused age-dependent spontaneous splenomegaly and, upon allosensitization, elevated CD4+/CD8+ T-cell ratios, enlarged germinal centers with heightened IL-21/Tfh activity, and augmented alloantibody production." (PMID 41896526, 2026). "Thus far, thrombocytopenia has been mostly associated with splenomegaly; however, the loss of naïve CD4+ T-cells is a stronger predictor than splenomegaly." (PMID 28054583, 2017). "The main characteristics associated with opportunistic disease (infectious or neoplastic) were lymph node > 5 cm, CD4 count < 200/mm3, hepatomegaly or splenomegaly and the presence of extra-ganglionic symptoms." (PMID 40982488, 2025). "A significant reduction in splenomegaly was also observed, along with significant reductions in CD4+ T helper 1 (Th1) and Th17 cells in the spleen." (PMID 40429822, 2025). "At 12 weeks upon engraftment a clear splenomegaly was confirmed and the presence of over 40% of PD1high CD4 + malignant cells was detected in one mouse of the cohort." (PMID 39272178, 2024). "The adoptive transfer of CD4+Foxp3+ or CD4+Lrig1+ T cells markedly alleviated the IBD symptoms such as body weight loss, inflammation in the colon, splenomegaly, and histological score, while these IBD symptoms were observed in CD4+Lrig1− T cell recipients." (PMID 37666819, 2023). "Any abnormal immunological features such as splenomegaly or inflammatory CD4+ T cell population in lymph nodes and lungs were undetected." (PMID 37666819, 2023). "Female mutants developed splenomegaly earlier, and also displayed more robust increases in MP CD4 cells between 9-15 weeks." (PMID 37275873, 2023). "Anti-CD4 antibody treatment, while having little effect on most measures, was highly effective at preventing splenomegaly." (PMID 37156988, 2023). "Then, analysis on spleen cells showed that NCTD significantly attenuated splenomegaly accompanied with the reduced percentage and number of T cells especially DN T cells and CD4 + T cells." (PMID 34552214, 2022). "ApcMin mice with intestinal adenomas develop splenomegaly associated with lymphodepletion of CD3, CD4, and CD8 T cells and natural killer cells." (PMID 36860494, 2022). "It was observed that cutaneous vasculitis, low C3 and C4 levels, cryoglobulinemia, low CD4 to CD8 ratio, persistent parotid gland enlargement, splenomegaly, and lymphadenopathy are significant risk factors for the development of non-Hodgkin lymphoma." (PMID 36253840, 2022). "Due to the splenomegaly in Ifnar1-/- mice, we still observed elevated total splenic CD4+ T cell counts in PbA-infected Ifnar1-/- mice in comparison to infected WT mice." (PMID 34659202, 2021). "On the other hand, prior infusion of MSCs prevented splenomegaly and accumulation of various cell types in the spleen, which in turn restored the abundance of CD4+ and CD8+ T lymphocytes." (PMID 33298881, 2020). "As anticipated, recipients showed accumulation of ICN-GFP+ and CD4+ CD8+ DP T-cells in BM associated with rapid increase of white blood cell (WBC) counts, DP T-cells in peripheral blood (PB), and splenomegaly." (PMID 31772299, 2020). "The numbers of splenic CD8+ and CD4+ T cells were significantly increased in 4X infected mice compared with 1X infected mice on day 8 of infection, contributing to splenomegaly in 4X infected mice." (PMID 30846985, 2019). "Analyses of cell lineages using flow cytometry indicated that splenomegaly in Sle1Tg7 mice was characterized primarily by CD11b+ myeloid and CD4+ T cell expansion." (PMID 31354711, 2019).
Splenomegaly (continued). "As expected, both Treg and CD4+Foxp3– T cells from the Tet2/3fl/flFoxp3Cre mouse with less severe splenomegaly more closely resembled the corresponding WT cells, whereas cells from the mouse with more severe splenomegaly were less similar to WT." (PMID 31043609, 2019). "Tet2/3fl/flFoxp3Cre mice develop an inflammatory disease with splenomegaly and leukocyte infiltration into lung, and CD4+Foxp3+ Treg cells, CD4+Foxp3− and CD8+ T cells in these mice display an activated phenotype." (PMID 31043609, 2019). "Mice pretreated with S4B6/IL-2 complexes had increased splenomegaly as well as significantly higher numbers of donor CD4+ T cells with a central memory phenotype." (PMID 29670626, 2018). "The resulting linear model included only 2 predictors of TC: “splenomegaly” and “% Naive CD4+ T-cells”." (PMID 28054583, 2017). "Although both predictors were able to significantly predict the TC separately (splenomegaly p < 0.02, Naive CD4+ T-cells p < 0.0004), only naive CD4+ T-cells remained a significant predictor in a multivariate model (p < 0.001)." (PMID 28054583, 2017). "Inspection of lymph nodes and spleen and quantitation of CD4+, CD8+ and CD4−CD8−B220+ DN T cells showed that the Fas C194V transgene completely protected mice from the lymphadenopathy and splenomegaly that arises in Fas-deficient lpr/lpr mice." (PMID 28008916, 2016). "The second was HIV positive with CD4+ T cell count 180/microliter and lymphadenopathy in the neck and axilla and mild splenomegaly." (PMID 26075117, 2015). "Further, in vivo silencing of miR-21 by seed-targeting LNA altered the ratios of CD4/CD8 T-cell-reversed splenomegaly and reduced the number of Fas receptor-expressing lymphocytes." (PMID 25927578, 2015). "The splenomegaly was characterized by expansion of both CD4+ and CD8+ T cells, providing evidence of a systemic inflammatory T cell response after infection and Treg depletion." (PMID 23926350, 2013). "After intravenous infection with Mtb, splenomegaly was observed in all groups, with an almost fivefold increase in the total number of CD4+ T cells." (PMID 24250805, 2013). "Compared to age- and sex-matched B6 mice, MRL/lpr mice exhibited splenomegaly with expansion of CD4+CXCR5+PD-1+ Tfh cells." (PMID 23638156, 2013). "It was reported that HTLV-1 infection increased the number of CD25+CD4+ T cells and resulted in splenomegaly." (PMID 22969759, 2012). "Intra-renal immunotherapy also led to systemic immune responses characterized by splenomegaly, elevated serum IgG levels, increased CD4 and CD8 T cell infiltration into the lungs, and elimination of metastatic lung tumors." (PMID 22312440, 2012). "Both types of donor CD4+ T cells were similarly protective against severe FV-induced splenomegaly that otherwise develops in these hosts." (PMID 22589728, 2012). "A rapidly fatal disease of a 12 years old boy presenting with sinusoidal pattern of paraoaortic nodal involvement, thrombocytopenia, splenomegaly and BM involvement was s100p+ CD4+ CD8- TCL." (PMID 17335572, 2007). "However, although splenomegaly was similar between primary NMI-infected B cell deficient and T cell deficient mice, it was significantly higher than NMI-infected WT, CD4+ T cell deficient and CD8+ T cell deficient mice." (PMID 39469719, 2024). "This notion is supported by a study of CII-immunization in TNF deficient mice, which reported the development of splenomegaly, increased splenic memory CD4+ T cells, but not B cells, and impaired IgG class switching in comparison to wt CII-immunized mice." (PMID 35216345, 2022). "However, although splenomegaly was similar between NMII-immunized B cell-deficient and T cell-deficient mice, it was significantly higher than NMII-immunized WT, CD4+ T cell-deficient, and CD8+ T cell-deficient mice." (PMID 34795669, 2021).
Splenomegaly (continued). "Many aspects of chronic HTLV-1 infection in humans were observed in this model, such as splenomegaly, proliferation of effector/memory CD4+ and CD8+ T-cells and polarization of the immune response to T-cell phenotypes associated with the expression of CXCR3 and CCR5." (PMID 34685494, 2021). "To confirm whether splenomegaly could be due to cell attraction in relation with induced Th1 response, we performed tissue staining to estimate CD4+ T cells, CD8+ T cells, and CD20+ B lymphocyte infiltrates." (PMID 31870416, 2019). "In mice infected with L. donovani, CD4 T cell activation can be detected in the first day after infection and the pool of parasite-specific splenic CD4 T cells increases several fold during the first weeks contributing to splenomegaly." (PMID 26932389, 2016). "Interestingly, however, at an older age (4 months old), the Tbk1-TKO mice had splenomegaly and higher splenocyte numbers as well as increased numbers of CD4+ and CD8+ T cells in different lymphoid organs and the peripheral blood." (PMID 25606824, 2015). "B6.IDO−/− mice infected with LP-BM5 retrovirus succumbed to MAIDS as indicated by splenomegaly, serum hyper IgG2a and IgM, decreased responsiveness to B- and T-cell mitogens, conversion of a proportion of CD4+ T cells from Thy1.2+ to Thy1.2-, and increased percentages of CD11b+Gr-1+ cells." (PMID 23680027, 2013). "In terms of absolute numbers, we have found that Stat1−/− mice have essentially normal numbers of Foxp3+ cells, but these mice have profound splenomegaly and approximately ten times more CD4+ T cells with an activated phenotype (CD25+ Foxp3−) than wild-type controls (not shown)." (PMID 18792404, 2008). "Notably, CD4+ T cell levels rose in the spleen and declined in lymph nodes, likely due to prolonged antigen exposure and T cell redistribution, potentially leading to splenomegaly." (PMID 40733014, 2025). "Thus, a reduced CD4/CD8 ratio is consistent with decreased splenomegaly with ambient QAC exposure." (PMID 33193366, 2020). "Regarding hepatopathy and splenomegaly, we observed increased CD57+ CD8 T cells, activated HLADR+ CD8 T cells, and HLA-DR+ CD4 T cells and reduced naïve CD45RA+ CD4 T cells." (PMID 40496855, 2025). "These risk factors included age, fever, cough, skin lesions, POAL, hepatomegaly, splenomegaly, oral candidiasis, bacterial pneumonia, Hb, WBC, PLT, elevated ALT, elevated AST, AARI, and CD4+ T cell count (P < 0.1)." (PMID 39635857, 2024). "In the present study, WCP significantly increased the proportion of CD4+ and CD8+ T lymphocytes as well as macrophages (p < 0.05) and alleviated H22-tumor-induced thymic atrophy (p < 0.05) and splenomegaly (p < 0.05)." (PMID 37110586, 2023). "Mice receiving naïve CD4 T cells + IRS1-overexpressing Treg cells also had shorter colons, developed splenomegaly, and had thicker epithelial layers." (PMID 36768873, 2023). "In agreement with characteristics observed in humans, high HTLV-1 PVL, splenomegaly, and high CD25 expression in CD4+ T-cells were observed in this mouse model." (PMID 34685494, 2021). "Acute GVHD induced by C57Bl/6 splenocytes injection to CBF1 mice (F1: CBA×C57Bl/6) was accompanied by splenomegaly, expansion of CD3+ and CD8+, and reduction of CD19+ and CD4+ spleen lymphocytes, which are known to be acute GVHD signs." (PMID 32953894, 2020). "As compared to the DN (CD4−CD8−) phenotype of T cells expanding in lymphoid tissue and responsible for the profound lymphadenopathy and splenomegaly exhibited by MRL/lpr mice, T cells infiltrating the CP were preferentially CD4+ or CD8+ single positive cells." (PMID 29593732, 2018). "Rottlerin effectively limited the splenomegaly induced by IMQ and altered the percentages of CD3+CD4+ T cells and CD3+CD8+ T cells in the spleen and skin, while ameliorating of imiquimod-induced psoriasiform inflammation." (PMID 29272319, 2017).
Splenomegaly (continued). "Whereas ATM-/- mice developed thymic lymphomas, the compound mutant mice developed splenomegaly marked by an accumulation of CD3+ cells that were of a CD4+ subtype." (PMID 26544571, 2015). "Similar to the observations seen with the spleens of mice receiving quiescent T cells, the splenic count of CD4 T cells was higher in non-responders, echoing the splenomegaly recorded in this group." (PMID 40896578, 2025). "Both the CTRL-DSS and MV130-DSS animals presented an evident splenomegaly as early as 4 days after the induction with DSS, becoming statistically significant on day 7 when a generalised increase in total splenocytes and CD4+ T lymphocytes was observed in both groups of animals." (PMID 39769391, 2024). "It is marked by lymphadenopathy, splenomegaly, hyperlymphocytosis, and the presence of circulating CD4-/CD8- double-negative T cells." (PMID 39796139, 2024). "Additionally, positive correlations were revealed between PD-L1+CD4+ and PD-L1+CD20+ lymphocytes and splenomegaly (p = 0.093 and p = 0.015)." (PMID 37766150, 2023). "In Hashimoto’s article, patients with splenomegaly have a higher number of CD4+ regulatory T cells, PD-L1, and PD-L2 expression cells than those without splenomegaly, implying that patients with splenomegaly have poor tumor immunity." (PMID 35686100, 2022). "A lower frequency of CD4+ T cells in spleens of infected mice was detected, although their number was higher than in non-infected mice, likely due to prominent splenomegaly in response to the infection." (PMID 36271272, 2022). "Although both disorders exhibit signs of substantial inflammation, KICS has minimal lymphadenopathy/splenomegaly and negative pathologic nodal changes in the setting of low CD4 count." (PMID 32724735, 2020). "We also demonstrate that Irf5 expression in CD11c+ cells is essential for inducing splenomegaly, but it is not required for the development or maintenance of parasite-specific IFNγ-producing CD4 T cells." (PMID 32038622, 2019). "Both CD4+ and CD8+ T cells are found in minimal proportions during splenomegaly, while non-T CD4−/CD8− cells take the leading role in abundance." (PMID 30728824, 2018). "TLR7[Tg] and R2-Yaa animals exhibit splenomegaly and peripheral lymphocyte expansion of B cells and CD4+ T cells, but no significant peripheral CD8+ T cell expansion." (PMID 28098193, 2017). "We also observed that exhaustion and activation markers in CD4+ and CD8+ T cells, respectively, do not seem to be associated with splenomegaly, a predominant clinical feature of CVID (43.7 % of selected patients)." (PMID 27188997, 2016). "Therefore, Blimp-1-dependent IL-10 produced by CD4+ T cells acts on myeloid cells, including MZM, to impair parasite killing, but also acts to limit splenomegaly." (PMID 26765224, 2016). "CD4+ T cells are required for MHV-68-induced splenomegaly, while CD8+ T cells are critical for limiting productive pulmonary infection and for the resolution of splenomegaly." (PMID 25324959, 2014). "Despite the drastic increase in splenic CD4 T cells, the occurrence of splenomegaly was not evident in infected animals during the course of the experiments (not shown)." (PMID 24763747, 2014). "Autoimmune lymphoproliferative syndrome (ALPS) is caused by genetic defects decreasing Fas function and is characterized by lymphadenopathy/splenomegaly and expansion of CD4/CD8 double-negative T cells." (PMID 23840885, 2013). "In addition to reduced body weight, old but not young Tdrd3-deficient Treg mice also exhibited splenomegaly, with markedly increased spleen weight and total cellularity, together with an increased CD3+ T cells, including both CD4+ and CD8+ subsets." (PMID 41576154, 2026). "All other factors, namely platelet count, TLC, PB and BM blast %, BM cellularity and lymphocyte%, IPT, lymphadenopathy, hepatomegaly, splenomegaly, molecular genetics, cytogenetic risk stratification, CD34+, CD34+/CD38-, CD4+/CD3+, CD8+/CD3+, CD4/CD8 ratio and MRD had no impact on PFS." (PMID 40940644, 2025).
Splenomegaly (continued). "Overall, leniolisib induced a dose-related reduction in canonical clinical features of ALPS-FAS in the murine model, including lymphadenopathy, splenomegaly, and elevated CD4−/CD8− DNTs in blood, spleen, and lymph nodes, and thus reduced the overall disease burden." (PMID 41608120, 2025). "An initial assessment of the immune phenotype of apoE KO mice revealed that these mice display splenomegaly with an accumulation of CD4+CD44hiCD62Llo T cells (effector memory, TEM) but not of CD8+CD44hiCD62Llo in the spleen, and a concomitant decrease of CD4+CD44loCD62Lhi T cells (Tnaive)." (PMID 30082772, 2018). "In addition to splenomegaly, a massive proliferation of CD4/CD8 double-negative (DN) T cells is characteristic for MRL/lpr mice." (PMID 27770825, 2016). "Autoimmune lymphoproliferative syndrome (ALPS) is another genetic lymphoproliferative disease and is characterized by lymphadenomegaly and/or splenomegaly, due to polyclonal accumulation of lymphocytes, and peripheral expansion of CD4/CD8 double-negative (DN) T cells." (PMID 23840885, 2013). "However, unlike in Lyn-/-IL-10-/- mice, there was no enhancement of splenomegaly, CD4+ T cell activation (as measured by CD69 expression), CD4 T cell naïve and effector memory frequencies, or myeloid expansion in Lyn-/-.Ighg3-cre.DTA and Lyn-/-.Ighg3-cre.IRF4f/f mice compared to Lyn-/- controls." (PMID 41445737, 2025). "Interestingly, even if similar degrees of splenomegaly that correlated with similar numbers of CD3+ T-cells in the spleen were detected, it remains that the number as well as the percentage of CD4+CD25+ T-cells among human splenocytes were higher in WT than in ΔPBM hu-mice." (PMID 29566098, 2018). "The Fcrl5 Tg mice showed more progressive splenomegaly (data not shown) and increased numbers of CD19+ B cells and CD4+ T cells than WT mice." (PMID 37841260, 2023). "The absence of B cells in RAG-/- hosts prevented splenomegaly and T cell expansion, which was only seen in LAT-/- host upon transfer of ERCre+LATf/m CD4+ T cells." (PMID 33912184, 2021). "In spite of no evident splenomegaly, a 2-3-fold increase in the number of CXCR3+ CD4+ and CD8+ T cells was observed in IP-10−/− mice compared to controls." (PMID 19343215, 2009). "Interestingly and consistent with the ELISA data, the percentages of IL-10-producing CD4+ cells were not different between WT and Bam32-/- mice, although the absolute numbers were higher than those from WT mice, which could be due to higher splenomegaly during the late stage of infection." (PMID 25875604, 2015).